FADS1 (fatty acid desaturase 1)
Diseases named in the same sentence as FADS1 in open-access papers (continued):
Sharing a sentence is not in itself a finding about the gene and the disease.
cancer (48 papers, 2011 to 2025). A tumor composed of atypical neoplastic, often pleomorphic cells that invade other tissues. "In summary, our study highlighted that FADS1 is a key gene broadly involved in cancer risk, biology, and patient prognosis." (PMID 36046053, 2022). "Our analyses demonstrated that FADS1 mRNA level in the tumor is significantly associated with cancer patient survival." (PMID 36046053, 2022). "The genes that had significantly different RNA expression levels of FADS1 between mutated and wild-type in at least one individual cancer type were considered." (PMID 36046053, 2022). "Our in vitro studies demonstrated that reduced FADS1 expression or activity is indeed causally integral to cancer cell proliferation." (PMID 36046053, 2022). "Our in vitro assay further validated the causal role of FADS1 in regulating cancer cell proliferation and suggested that pharmacological inhibition of FADS1 can be a novel strategy for anti-cancer treatment." (PMID 36046053, 2022). "Taken together, our data suggested that FADS1 is causally involved in cancer cell proliferation, thus can be a pharmacological target for anti-cancer treatment." (PMID 36046053, 2022). "PUFA status in plasma/tissues and its association with FADS1/FADS2 polymorphism in cancer patients." (PMID 40430008, 2025). "PUFA status and FADS1/FADS2 genotypes as potential risk factors for cancer development." (PMID 40430008, 2025). "To investigate the detailed molecular mechanisms of how FADS1 expression is underlying the associations discovered above, we identified genes that are significantly correlated with FADS1 RNA level in all cancers as a whole and in each cancer type, using Spearman’s correlation." (PMID 36046053, 2022). "Less FADS1 and 2 activity leads to a reduction in long chain omega-6 fatty acids and a less pro-inflammatory tissue milieu that may aid in reducing cancer risk and growth promotion." (PMID 36581893, 2022). "We aim to examine whether FADS1 expression is associated with cancer patient survival." (PMID 36046053, 2022). "Given the significant increase in ATF3 expression in response to FADS1 inhibition, we set out to further investigate the potential role of ATF3 in mediating the impact of FADS1 inhibition on cancer cell growth." (PMID 40121894, 2025). "To determine if FADS1 is critical for protection of cancer cells from extreme ER stress and the maintenance of cancer cell survival and growth, we pretreated 786-o and A498 cells with TM (1 ng/mL) for 18 hrs." (PMID 40121894, 2025). "One study showed that knockdown of FADS1 inhibits the proliferation, migration, and invasion of cancer cells." (PMID 40140093, 2025). "FADS1/2 regulate lipid metabolism and ferroptosis sensitivity in triple‐negative breast cancer cells, serving as potential targets for cancer therapy." (PMID 40919133, 2025). "Several genes altered during activation are approved or potential drug targets, including HMGCR, FADS1/2 and CPT1A, while others, such as FASN, CD36, and CTSD, are directly implicated in cancer-related processes." (PMID 40759959, 2025). "This review examines the existing literature on FADS1/2 SNP variations in cancer patients, focusing on their impact on PUFA metabolism, concentrations in both blood and malignant tissues, and the potential implications for disease risk." (PMID 40430008, 2025). "While genetic variations in the FADS1 and FADS2 genes are linked to PUFA metabolism and cancer risk, the interplay between dietary PUFA intake and genetic factors remains insufficiently understood." (PMID 40430008, 2025). "Dietary supplementation of omega-3 fatty acids, along with genetic variants in the FADS1/FADS2 gene clusters, in cancer patients." (PMID 40430008, 2025).
cancer (continued). "A review of the literature on PC metabolism in various cancers revealed that FADS1, FASN, PCYT1A, LPCAT1, and PLD2 are involved in PC metabolism in multiple cancers." (PMID 40148316, 2025). "We further provide evidence that FADS1 is essential for supporting cancer cell growth by protecting cancer cells from persistent ER stress, which is mediated by the PERK-ATF4 pathway with the involvement of a key transcription factor ATF3." (PMID 40121894, 2025). "We further provide evidence that FADS1 is essential for supporting cancer cell growth by protecting cancer cells from persistent ER stress, which is mediated by a key transcription factor ATF3." (PMID 38586033, 2024). "To determine if FADS1 is critical for protection of cancer cells from acute ER stress and the maintenance of cancer cell survival and growth, we pretreated 786-o and A498 cells with TM (1 ng/ml) or TG (1 nM) for 18 h." (PMID 38586033, 2024). "Conversely, the down-regulated DEGs are linked to pathways associated with cancer or immune responses, in alignment with previous findings, such as SCD1, ELOV2, FADS1, FADS2, and BMP6." (PMID 38693536, 2024). "Our findings suggest that PUFA desaturation is crucial for rescuing cancer cells from persistent ER stress, supporting FADS1 as a new therapeutic target." (PMID 38586033, 2024). "Increasing evidence suggests that FADS1 activity and PUFA metabolism are closely linked to cancer initiation, progression and metastasis." (PMID 38586033, 2024). "The FADS1 transcription level is even higher in metastatic and recurrent tumors, highlighting its potential role in cancer biology and disease progression." (PMID 38586033, 2024). "FADS1 has gained attention in cancer biology as it is overexpressed in a variety of cancers and its levels are associated with tumor grade and prognosis." (PMID 38522521, 2024). "Cumulatively, we report a potential cancer-promoting mechanism of FADS1-AA axis in CRC that converts raising synthesized AA to PGE2 via modulating the intestinal microecology of gram-negative." (PMID 37041160, 2023). "Our data showed the increased enrichment of 13C-AA and estimated FADS1 activity in the high-invasive cancer cells." (PMID 38136676, 2023). "This comprehensive analysis indicated that among all cancer patients, those with a higher FADS1 mRNA expression in their tumor have a significantly worse OS and DFS (P= 0.002 and P<0.001, respectively)." (PMID 36046053, 2022). "We found that FADS1 mRNA level was significantly increased in tumors, especially in metastatic or recurrent ones, than that in normal tissues among all cancers." (PMID 36046053, 2022). "Our study suggests that FADS1 plays multiple roles in cancer biology and is potentially a novel target for precision cancer treatment." (PMID 36046053, 2022). "Herein, we used TIMER2.0 tool to demonstrate the relationship between immune cell filtration and FADS1 expression in TCGA cancer types." (PMID 36046053, 2022). "Increasing evidence has suggested that FADS1 and its controlled LC-PUFA metabolism play important role in cancer risk, biology and progression." (PMID 36046053, 2022). "A total of 709 unique eQTLs (associated with FADS1 mRNA expression in at least one cancer type with a nominal P<0.05) for FADS1 have been identified in TCGA among all cancer types." (PMID 36046053, 2022). "In this study, by using the TCGA database, we performed a comprehensive analysis to investigate the role of FADS1 as a key player in 32 types of cancers." (PMID 36046053, 2022). "We found that FADS1 expression was significantly increased in tumors and especially in metastatic or recurrent tumors than in normal tissues among all cancer samples." (PMID 36046053, 2022). "Our study demonstrated that FADS1 is a marker for cancer survival, which is potentially driven by a unique molecular mechanism." (PMID 36046053, 2022).
cancer (continued). "Utilizing The Cancer Genome Atlas (TCGA) database, we explored the role of FADS1 across different cancer types using multiple bioinformatics and statistical tools." (PMID 36046053, 2022). "Tumors with increased FADS1 expression also demonstrated an increased signatures of fibroblasts and macrophages infiltration among most cancer types." (PMID 36046053, 2022). "Our study for the first time demonstrated that FADS1 is a marker correlated with prognostic outcomes of cancer patients in multiple cancer types." (PMID 36046053, 2022). "We found that known eQTLs of FADS1 gene among five cancer types still remain to be its eQTLs in tumor tissues." (PMID 36046053, 2022). "Previous studies have shown that the expression of FADS1 was dysregulated in many cancers and that knockdown of FADS1 not only inhibited cancer growth and migration but also enhanced the cytotoxicity of chemotherapeutic agents." (PMID 32332698, 2020). "FADS1 knockdown not only inhibited cancer growth and migration but also enhanced the cytotoxicity of chemotherapy drug." (PMID 32332698, 2020). "Genes coding for the fatty acid desaturases (FADS1, 2, 3) localized at the cancer genomic hotspot 11q13 locus are required for the biosynthesis of 20 carbon polyunsaturated fatty acids (PUFA) that are direct eicosanoid precursors." (PMID 22140540, 2011). "Moreover, according to available data, FADS1 is causally involved in cancer cell proliferation and, together with FADS2, has emerged as a promising pharmacological target for anti-cancer therapy." (PMID 40430008, 2025). "Taken together, these findings suggest that ALA and EPA, as FADS1-targeting nutritional agents, may represent promising candidates for anti-cancer therapy." (PMID 41153716, 2025). "Patients with high FADS1 expression may benefit from FADS1-targeted therapies, as inhibition has been shown to suppress cancer cell growth." (PMID 40430008, 2025). "This review aimed to investigate the relationship between FADS1 and FADS2 gene variants and dietary intake, supplementation, or intervention with omega-3 fatty acids, gamma-linolenic acid (GLA), or their combination in cancer patients." (PMID 40430008, 2025). "Increasing studies suggest that FADS1 is a potential cancer target." (PMID 40121894, 2025). "Notably, FADS1-inhibition sensitized cellular response to ER stress inducers, providing evidence of FADS1’s role in modulating the ER stress response in cancer cells." (PMID 38586033, 2024). "Also, some studies have demonstrated that FADS1 inhibition or reduced expression enhances cancer cell sensitivity." (PMID 38586033, 2024). "Taken together, these results demonstrate that reduced FADS1 function limits tumor formation in vivo, suggesting inhibiting FADS1 might have a therapeutic potential for cancer." (PMID 38586033, 2024). "FADS1 expression is higher in GBM cancer stem cells than in other GBM cancer cells." (PMID 36765904, 2023). "Increased FADS2 expression has been observed in certain cancers and may offer a mechanism of increased metabolic plasticity, suggesting increased FADS1 and/or FADS2 activity may result in therapeutic resistance in relapsed AML." (PMID 37110126, 2023). "In addition, we also found evidence that adipocytes co-cultured with cancer cells had a diminished expression level of FADS1, which encodes the delta-5 desaturase, one of the key enzymes in polyunsaturated fatty acid synthesis." (PMID 37316878, 2023). "FADS1 is identified as an independent cancer prognostic factor in a few studies." (PMID 36046053, 2022). "We identified that FADS1 gene is a predictor for cancer survival in multiple cancer types." (PMID 36046053, 2022). "Our in vitro assays demonstrated that pharmacologically inhibiting FADS1 function indeed reduced cancer cell proliferation, suggesting that FADS1 could be a new target for cancer treatment." (PMID 36046053, 2022). "Moreover, we studied the impact of a FADS1 inhibitor (D5D-IN-326) on proliferation of multiple cancer cell lines." (PMID 36046053, 2022).
cancer (continued). "Thus, we hypothesized that inhibition of PUFA desaturation by targeting FADS1 would also induce ER stress and subsequently hinder the cancer cell growth." (PMID 40121894, 2025). "Similarly, FADS1 is upregulated in some cancer and effectively mediates PUFA synthesis." (PMID 39145825, 2025). "Since the data on PUFA metabolism and FADS polymorphisms remain inconclusive, this review aimed to examine the influence of FADS1 and FADS2 gene variants on metabolism and biological effects of omega-3 fatty acids and gamma-linolenic acid, both individually and in combination, in cancer patients." (PMID 40430008, 2025). "Thus, we hypothesized that inhibition of LC-PUFA desaturation by targeting FADS1 would also induce ER stress and subsequently hinder the cancer cell growth." (PMID 38586033, 2024). "However, the role of FADS1 in cancers remains incompletely understood." (PMID 36046053, 2022). "FADS1 is a member of the fatty acid desaturase gene family and has been suggested to regulate inflammation by modifying the metabolite profiles of fatty acids, which may influence the progression of cancer." (PMID 30175151, 2018). "Previous research has shown that Fatty Acid Desaturase 1 (FADS1), a rate-limiting enzyme directly controlling the bioproduction of AA and EPA, plays a significant role in the growth of various cancer cells." (PMID 40121894, 2025). "Higher FPKM values for FADS1, ELOVL5, and ACLY were detected in cancer tissues than in adjacent normal tissues (P < 0.01; P < 0.01; P < 0.01), suggesting that alterations in lipid metabolism in ESCC are mediated by altered expression of these genes." (PMID 41184824, 2025). "This was accompanied by the upregulation of key enzymes involved in synthesis (FASN), elongation (ELOVL1,2,5,6,and 7), and desaturation (FADS1 and FADS2) in ovarian tissue compared to NC groups, implicating these pathways in cancer progression." (PMID 40371224, 2025). "FADS1, as the rate-limiting enzyme of PUFA synthesis, catalyzing DGLA to AA, was reported to be frequently dysregulated in cancers." (PMID 32332698, 2020). "Additionally, research has shown the upregulation of other PUFA synthesis enzymes in cancer cells, such as elongation of very long-chain fatty acid protein 5 (ELOVL5) and fatty acid desaturase 1 (FADS1)." (PMID 40709182, 2025). "A secondary objective was to examine genetically determined fatty acid profiles—shaped by FADS1 and FADS2 polymorphisms—in cancer patients without intervention and their potential association with PUFA-related cancer risk." (PMID 40430008, 2025). "For example, miR-1908, located in the first intron of FADS1, was not coexpressed with FADS1 in any cancer types." (PMID 34572448, 2021). "We then verified the FADS1 mRNA expression and found that the mRNA level of FADS1 was enhanced in 30 LSCC cancer tissues than that in paired nonneoplastic tissues by qRT-PCR." (PMID 32332698, 2020). "Indeed, of the eight CRC GWAS loci found within this subset of CRC-related smoking genes, CDCA8, CDKN3, FADS1, FADS2, MYBL2, PCSK9, and PRC1, have all been reported to be overexpressed in others cancers and to play important roles in the DNA damage response pathway." (PMID 37509213, 2023). "However, the role of FADS1 in different cancers has not been systematically explored." (PMID 36046053, 2022). "The mRNA levels of ELOVL4, ELOVL5 and FADS2 were increased in cultured cancer cells comparing to normal colon cells, but we did not detected the expression of ELOVL2 and FADS1 in these cells." (PMID 32029824, 2020). "The mRNA levels of ELOVL4 and 5, as well as FADS2 were higher in cancer cells than in normal colon cells, but we did not detected the expression of ELOVL2 and FADS1 in these cells." (PMID 32029824, 2020).
tumor (25 papers, 2015 to 2025). "Elevated FADS1 expression is associated with poor prognosis, tumor progression, and an altered tumor microenvironment." (PMID 40430008, 2025). "Given the association between FADS1 expression and patient survival, it is important to have readily available markers to predict the FADS1 expression in tumor cells." (PMID 36046053, 2022). "This might indicate that increased FADS1 expression is associated with tumor aggressiveness, which may explain at least in part, its association with patient survival." (PMID 36046053, 2022). "This indicates that increased FADS1 expression is associated with tumor recurrence and metastasis, which may be underlying its association with patient survival." (PMID 36046053, 2022). "The expression levels of key enzymes involved in unsaturated fatty acid metabolism (Fads2, Elovl5, Fads1, Elovl2) were significantly altered in the liver and tumor tissues of the HUFA-gavaged mice." (PMID 39941731, 2025). "One study investigated the impact of genetic variations in FADS1/2 on circulating fatty acids, and another analyzed desaturase expression in both tumor tissue and peritumoral regions of GBM." (PMID 40430008, 2025). "Mechanistically, we demonstrated that FADS1 plays a reciprocal role in ER stress and downregulation results in inhibition of tumor growth through induction of PERK/eIF2α/ATF4/ATF3-mediated ER stress response." (PMID 40121894, 2025). "Functional validation using FADS1-knockout cell lines and mouse models demonstrated that FADS1 inhibition suppresses tumor cell proliferation, migration, and invasion while promoting apoptosis." (PMID 41102141, 2025). "Our in vivo mouse tumorigenesis experiments further indicate that limiting FADS1 expression reduces tumor formation and growth." (PMID 40121894, 2025). "Cell-type-specific expression of FADS1 differed significantly between the tumor and adjacent tissues." (PMID 41153716, 2025). "Conversely, in hypopharyngeal carcinoma, downregulation of LINC01569 inhibits macrophage M2 polarization through miR-193a-5p/FADS1 signaling, aiding tumor cells in evading immune surveillance and promoting tumor progression." (PMID 40161373, 2025). "In vivo, FADS1 deletion reduced chemically induced CC/EC tumor burden by 62-75%, accompanied by decreased Ki-67/MMP-9 expression and inflammatory infiltration." (PMID 41102141, 2025). "Our in vivo mouse tumorigenesis experiments further indicate that reduced FADS1 expression reduces tumor formation and growth." (PMID 38586033, 2024). "Mechanistically, we show that FADS1 downregulation results in inhibition of tumor growth through induction of ATF3-mediated ER stress response." (PMID 38586033, 2024). "The weight of tumor xenografts derived from the FADS1-KD or control cells demonstrated a similar trend as the tumor size." (PMID 38586033, 2024). "To assess the impact of FADS1 on tumor development in vivo, we injected wild-type (WT) and FADS1-KD 786-o cells into the flank of male and female severe combined immunodeficient (SCID) mice to generate tumors." (PMID 38586033, 2024). "An in vivo orthotopic model was established using CRC cells and the organoid model, and FADS1 knockdown was found to significantly suppress orthotopic tumor growth." (PMID 37041160, 2023). "Functionally, FADS1 regulates CRC tumor growth via high AA microenvironment-induced enriched gram-negative microbes." (PMID 37041160, 2023). "In the orthotopic xenograft, the AA levels was significantly decreased in the interstitial fluid of tumor tissues in the shFADS1 group, compared with the shNC group, indicating FADS1 played a role in creating a high AA microenvironment." (PMID 37041160, 2023). "An analysis of clinical information demonstrated that high protein expression of FADS1 was positively correlated with tumor size, T stage, and pathological stage." (PMID 37041160, 2023). "We plotted the correlation between a representative SNP rs174556 and FADS1 mRNA levels among these tumor types as an example." (PMID 36046053, 2022).